INS (insulin)
Diseases named in the same sentence as INS in open-access papers (continued):
Sharing a sentence is not in itself a finding about the gene and the disease.
Hypoglycemia (continued). "A similar effect was seen in Ishikawa cells, except that additionally, insulin stimulation also caused an increase in PHLPP1 but only in hypoglycemia conditions." (PMID 36497428, 2022). "Non-insulin drugs provide a decrease in the fluctuation of glucose levels, important non-glycemic benefits, while also being associated with a lower risk of hypoglycemia compared to insulin therapy." (PMID 35315989, 2022). "The longer the interval between meal commencement and the prandial insulin bolus being delivered, the greater the risk of hypoglycemia." (PMID 32914648, 2022). "Better adherence to SMBG and higher education level were associated with hypoglycemia, while alcohol consumption, higher doses of basal insulin, and more frequent hospitalizations in the previous year were associated with SH." (PMID 36191264, 2022). "The first approach requires exogenous insulin or secretagogues drugs (such as sulfonylureas), whose administration is burdened by the risk of hypoglycemia." (PMID 35563608, 2022). "Potential factors can include the fact that insulin therapy stimulates appetite, genetic predispositions, dietary composition, the frequent need to treat hypoglycemia with high caloric drinks, and possible disordered eating in this population." (PMID 35873174, 2022). "It is likely that older people with multimorbidity were treated more with insulin to achieve lower HbA1c targets with a potential high risk of hypoglycaemia and uncertain long-term benefit." (PMID 36422087, 2022). "Increased insulin sensitivity associated with excessive circulating insulin levels and a frequently altered hormonal counter-regulatory response to hypoglycemia, predispose to nocturnal hypoglycemia, especially when PA is involved late in the afternoon." (PMID 36237197, 2022). "Personally, I prefer to eat low carb...keeps the dose of insulin and risk of hypos [hypoglycemia] low, helps you lose weight and takes the pressure off your pancreas." (PMID 36197724, 2022). "On the contrary, elevated concentrations of insulin can repress gluconeogenesis, thus enhancing peripheral penetration of glucose and cause an emergent medical condition called hypoglycemia." (PMID 35723344, 2022). "In vivo glycemic regulation ability of the GRS glucagon MN patch to lower hypoglycemia risks was further assessed with a streptozotocin (STZ) ‐induced insulin‐deficient diabetic mouse model." (PMID 35957510, 2022). "These second-generation basal insulin analogues have similar a metabolic effect compared to the first-generation analogues; though, second-generation insulins have a lower risk of hypoglycaemia." (PMID 36555450, 2022). "For patients with T2DM who use insulin therapy, perioperative and postoperative blood glucose monitoring should be strengthened to assess the risk of hypoglycemia." (PMID 35538461, 2022). "But as renal clearance of insulin decreases and the duration of insulin action prolongs, the risk of hypoglycemia gradually increases, and even cardiovascular and cerebrovascular events can be induced." (PMID 36177313, 2022). "Due to the increased risk of hypoglycemia in these patients when they are on intensive insulin therapy (basal-bolus regimen), a continuous interstitial glucose monitoring system should be considered." (PMID 36422243, 2022). "For glycemic control, when injectable therapy is needed, GLP-1 RAs are the preferred option to insulin since the risk of hypoglycemia and body weight gain are less than insulin therapy." (PMID 36559020, 2022). "The abrogation of the normal physiology of a preferential hepatic insulin action is one contributor to the risk of hypoglycemia with a basal insulin." (PMID 35177603, 2022). "It was emphasized that people using insulin and sulfonylurea should be alert because of the risk of hypoglycaemia." (PMID 36326405, 2022).
Hypoglycemia (continued). "Nevertheless, data reflect real-life practice and the barriers to optimize insulin doses, especially when patients or diabetologists are concerned by the risk of hypoglycemia." (PMID 35864262, 2022). "Similar observations have been made for KCNQ1-related long-QT syndrome, which has already been shown to be associated with insulin-mediated hypoglycemia." (PMID 35897673, 2022). "With features like these, insulin order sets in the EHR that include standing orders for hypoglycemia treatment have been associated with reduced rates of hypoglycemia." (PMID 35917098, 2022). "Factitious hypoglycaemia in non‐diabetic patients due to self‐administration of insulin or oral antidiabetic drugs represents a diagnostic challenge that continues nowadays to intrigue clinicians." (PMID 36117266, 2022). "In fact, the treatment switch from insulin to sulfonylureas was proven to improve patients’ glycemic control, as well as decrease the risk of hypoglycemia episodes." (PMID 36361703, 2022). "Patients taking HCQ concomitantly with metformin, acetylsalicylic acid, insulin, gliclazide, and escitalopram should be closely monitored for the risk of hypoglycemia." (PMID 37092113, 2022). "In patients with T1D and T2D treated intensively, risk factors for hypoglycemia include intensive insulin therapy, better glycemic control, physical activity, dietary errors, and alcohol consumption." (PMID 35324747, 2022). "Risk factors associated with severe hypoglycemia include age, insulin and sulfonylurea use, and cognitive impairment." (PMID 36034445, 2022). "Although insulin and glucagon like peptide-1 receptor agonist (GLP-1 RA) exert a good role in glycemic control in T2DM, unfortunately insulin has the risk of triggering hypoglycemia." (PMID 36119737, 2022). "As insulin use itself was associated with risk of severe hypoglycemia (aHR, 3.07; 95% CI, 3.00-3.14) (eTable 1 in the Supplement), NAFLD appears to have less additive association." (PMID 35195697, 2022). "Exercising with high peripheral levels of insulin raises hypoglycemia risk while lowering blood insulin helps normalize hormonal responses." (PMID 36992764, 2022). "Potential concerns include the fact that, although insulin administration can cause hypoglycemia and hypoglycemic seizures, the risks associated with administering insulin to this population of non-diabetic cats has not been described." (PMID 36350735, 2022). "The blood glucose of dogs reached the nadir 12-16 h after injection, which was caused by severe hypoglycemia caused by the release of insulin from damaged β-cells." (PMID 35978645, 2022). "Insulinoma is an insulin-secreting tumor that causes hypoglycemia due to inappropriately high insulin secretion." (PMID 35475064, 2022). "Use of CGM was associated with a greater number of alterations in the insulin regimen, improved glycemic control, and fewer episodes of hypoglycemia." (PMID 36992784, 2022). "Sulfonylurea derivates lower glucose by stimulating endogenous insulin production and consequently predispose to hypoglycaemia and weight gain." (PMID 34097240, 2022). "Only 44% of participants reported applying a carbohydrate- or insulin-based strategy to limit the risk of nocturnal hypoglycemia on ACT day." (PMID 36237197, 2022). "Every patient taking insulin—even basal-only regimens—should be prescribed glucagon to treat severe hypoglycemia, and the patient’s family members and other close associates should be trained in how to administer it." (PMID 34922811, 2022). "At the same time, medical staff who intend to use insulin during the perioperative period should receive strengthened special training related to hypoglycemia risk assessment and control." (PMID 35538461, 2022). "Although insulin overdose is the most common risk factor for hypoglycemia, there are more subtle endogenous actors in diabetic pregnancy, which impact hypoglycemia occurrence." (PMID 35207323, 2022).
Hypoglycemia (continued). "High-GI meal stimulates glycogenesis and lipogenesis then, an increased level of insulin in response to a high-GI meal causes hypoglycemia after 2–4 h." (PMID 36253802, 2022). "For most individuals with T1D, the use of rapid-acting or ultra-rapid-acting insulin analogues in the basal-bolus regimen IS RECOMMENDED to reduce the risk of hypoglycemia." (PMID 36510287, 2022). "Parents who use glucose-sensing devices linked to insulin pump delivery systems spoke of fear of PA-induced hypoglycaemia." (PMID 35627851, 2022). "Overall, 19.4% of patients were treated with only lifestyle changes, 43.5 with antidiabetics with a high risk of hypoglycemia (23.0% with insulin, 17.8% with sulfonylureas, 6.7% with glinides), and 37.6% with antidiabetic drugs with a low risk of hypoglycemia." (PMID 36079064, 2022). "The brisk rise in blood glucose stimulates a rapid and excessive insulin secretion with subsequent hypoglycemia." (PMID 35453666, 2022). "Clinical characteristics, molecular genetics, and annual data relating to glycemic control (HbA1c) and severe hypoglycemia of those with INS mutations were collected." (PMID 35518939, 2022). "Endogenously secreted insulin very rarely causes hypoglycemia (apart from instance of untoward pharmacologic stimulation) due to tight negative feedback of blood glucose and with a short half-life of insulin." (PMID 35177603, 2022). "Despite this, hypoglycemia remains one of the most consequential acute complications associated with insulin replacement therapy." (PMID 35336018, 2022). "Modeling the glucose dependent insulin response using a hysteresis model should reveal if a lag in insulin recovery to baseline levels exists and causes postprandial hypoglycemia." (PMID 36148302, 2022). "Insulin is generally indicated, despite being inconvenient to use and prone to causing hypoglycemia." (PMID 35992135, 2022). "It is modified to deliver a consistent level of plasma insulin over an extended duration to lower HbA1c and reduce the risk of hypoglycemia." (PMID 36483894, 2022). "The risk of hypoglycaemia is higher in patients treated with sulfonylureas and insulin than for other antidiabetic drugs." (PMID 35684097, 2022). "In critically ill patients receiving intravenous insulin the coefficient of GV was independently associated with 30-day mortality (OR = 1.23 for every 10% increase, p<0.001), even after adjustment for hypoglycemia, age, disease severity, and comorbidities." (PMID 35877766, 2022). "Females in the standard fixed dosing group (10 units of insulin) were associated with an increased risk of hypoglycemia (OR 3.2, 95%CI 1.1 to 9.1, p 0.03) compared to the weight-based insulin dosing group (≤ 10 units of insulin)." (PMID 36371171, 2022). "This means that the intranasal administration of insulin is able to reduce the risk of hypoglycemia, which explains the ineffectiveness or worsening effect of peripheral insulin administration." (PMID 35742986, 2022). "It should be acknowledged that utilizing analogs of basal insulin during Ramadan is recommended due to the relatively lower risk of hypoglycemia, as compared to regular human insulin." (PMID 36505246, 2022). "We describe a 96-year-old man with insulin-dependent type 2 diabetes mellitus who, despite insulin cessation, presented with recurrent hypoglycemia associated with confirmed inappropriate endogenous hyperinsulinemia." (PMID 35685218, 2022). "Changes or interruption in nutrition is one of the primary causes of hypoglycemia in the hospital, so indication and holding parameters for nutritional insulin administration orders should be included in every nutritional insulin order." (PMID 35917098, 2022). "Reports show that age, renal impairment, insulin use, sulfonylurea use, β-blocker, or fibrate are associated with a higher risk of hypoglycemia." (PMID 36687427, 2022).
Hypoglycemia (continued). "Therapy modification with low dose insulin or insulin secretagogue can be recommended to avoid the risk of hypoglycemia when co-administered with dapagliflozin." (PMID 36457541, 2022). "Because GLP-1RA action is glucose-dependent, they have a low risk of hypoglycemia, unless combined with sulfonylureas or insulin." (PMID 35865956, 2022). "Hypoglycemia can be induced by many causes, especially by an overdose of oral hypoglycemic agents or insulin in diabetic patients, leading to hyperinsulinemic hypoglycemia." (PMID 35282439, 2022). "The adjusted multivariable logistic regression analysis showed that premixed insulin-based regimen and microvascular compilation were significantly associated with hypoglycemia events." (PMID 36149907, 2022). "Another evolving avenue in research is the addition of glucagon to mitigate the risk of hypoglycemia and allow more aggressive insulin dosing." (PMID 35733769, 2022). "Several studies have demonstrated that the specific binding of VIP with VPAC2 receptors on β-cells can stimulate insulin secretion in a glucose-dependent manner, eliminating the risk of hypoglycemia." (PMID 36204104, 2022). "It is modified to deliver consistent levels of plasma insulin over an extended duration, and it has been shown to lower HbA1c levels and the risk of hypoglycemia." (PMID 36483894, 2022). "This class of drugs produces a significant reduction in HbA1c, as well as weight loss, reduction in systolic and diastolic blood pressure via its diuretic effect and lower risk of hypoglycemia compared to insulin secretagogues." (PMID 35718795, 2022). "Relative to insulin, glyburide had an increased risk of neonatal illness, respiratory distress, neonatal hypoglycemia, birth injury, increased birth weight, and macrosomia." (PMID 35195193, 2022). "Rapid-acting insulin analogs significantly reduce postprandial glycemic excursions and the risk of late postprandial hypoglycemia compared to human regular insulin and improve the quality of life." (PMID 36014822, 2022). "The randomized, head-to-head, parallel group BRIGHT study involving insulin-naïve patients with T2D demonstrated that Gla-300 and Deg-100 provided similar glycemic control improvements with relatively low hypoglycemia risk." (PMID 35864262, 2022). "These inhibitors have certain advantages as oral hypoglycemic agents, such as weight neutrality, less risk of hypoglycemia, and an insulin-independent mechanism of action as an oral hypoglycemic agent, when compared with other drugs, such as sulfonylureas." (PMID 35885395, 2022). "Adult-onset familial insulinomatosis is a rare disorder with recurrent, severe hypoglycemia caused by multiple insulin-secreting pancreatic tumors." (PMID 35406570, 2022). "It is important to note that increased mortality due to cardiovascular events associated with hypoglycemia suggests the need to restrict long-term use of drugs that affect insulin secretion (sulfonylurea medications and insulin)." (PMID 35629267, 2022). "Insulin analogs such as glargine have a lower risk of hypoglycemia and a lower association with risk of fractures than neutral protamine Hagedorn insulin." (PMID 36382752, 2022). "Hypoglycemia is associated with an increased risk of cardiac arrhythmia due to a mismatch between insulin and carbohydrate intake, alcohol, or exercise." (PMID 35047039, 2022). "One systematic review that we judged to be of critically low quality, performed meta-analyses and reported that alternative insulin dosing (defined as < 10 units) had lower odds associated with hypoglycaemia and severe hypoglycaemia." (PMID 35552566, 2022). "It is worth repeating the test to determine the appropriate insulin dose reduction per chilled product to reduce the risk of postprandial hypoglycemia." (PMID 35429987, 2022). "Concerns about the risk of hypoglycemia can prevent or delay the initiation or intensification of insulin therapy." (PMID 36149907, 2022).
Hypoglycemia (continued). "This parallels the findings in mouse SUR1 and Kir6.2 knockout models of complete loss of KATP, which lack persistent hypoglycemia and instead exhibit glucose intolerance and loss of insulin secretion as adults." (PMID 36458573, 2022). "Previous studies showed that modest amounts of caffeine or theophylline were associated with augmented counter-regulatory responses to insulin-induced hypoglycemia." (PMID 35784552, 2022). "The secondary objective is to assess treatment-related causes of hypoglycemia among American adults with T1DM or T2DM prescribed insulin and/or insulin secretagogues." (PMID 35025756, 2022). "Compared with insulin injection therapy, insulin pump therapy was associated with lower risks of severe hypoglycemia and diabetic ketoacidosis and better glycemic control during the most recent year of therapy." (PMID 36422210, 2022). "The therapy required involves a risk of severe hypoglycemia, with all its consequences, if the insulin dose is too high." (PMID 35265035, 2022). "Compared to diabetic patients who used other hypoglycemic regimens, patients who used a subcutaneous injection of insulin as a preoperative hypoglycemic regimen had 1.822 times increased risk of hypoglycemia." (PMID 35538461, 2022). "The common causes of hypoglycaemia in T1D include insulin overdose, irregular food intake, and improper physical activity." (PMID 36440205, 2022). "On the other hand, GCGKO mice have been reported to be susceptible to hypoglycemia on insulin administration." (PMID 35267952, 2022). "The capacity of rosinidin to preserve body weight loss is a result of an escalation in insulin secretion and subsequent hypoglycemia reaction." (PMID 35335923, 2022). "Persistent hypoglycemia in infancy is attributed to pituitary hormone deficiency, growth hormone deficiency, adrenal insufficiency, and, more notably, dysregulated insulin secretion by the pancreatic β-cells." (PMID 36292647, 2022). "Insulin and glucagon signaling are both dramatically dampened in Cavin1−/− mice, the Cavin1 deficiency leads to lethal neonatal hypoglycemia." (PMID 35723340, 2022). "Insulin therapy also necessitates self-injection and is associated with an increased risk of maternal hypoglycaemia and excessive maternal gestational weight gain (GWG)." (PMID 36131291, 2022). "Advanced settings had a real-world demonstration regarding hypoglycemia incidences associated with the initiation of different regimens of insulin, such as basal and short acting insulin preparations." (PMID 36149907, 2022). "In ESRD HD-dependent patients with type 2 DM, insulin dose reduction by 26% on the day of the HD session is associated with fewer hypoglycemia symptoms and reasonable glycemic control." (PMID 35755525, 2022). "For those who had been receiving mixed insulin at home, changing to a basal bolus regimen is recommended as it reduces hypoglycemia risk." (PMID 35246230, 2022). "Some tumors produce autoantibodies against insulin or the insulin receptor that cause hypoglycemia in the paraneoplastic setting." (PMID 35414906, 2022). "In our case, we made the diagnosis of IAS after excluding other causes of hypoglycemia, and due to the remission of hypoglycemia and insulin level after MTZ was withdrawn." (PMID 35758364, 2022). "Antidiabetic medications (ADM), especially sulfonylureas (SFU) and basal insulin (BI), are associated with increased risk of hypoglycemia, which is especially concerning among older adults in poor health." (PMID 35114955, 2022). "Analogue insulins are genetically engineered to overcome some of the limitations of NPH and lente insulin such as variable absorption, duration of effect and risk of hypoglycaemia." (PMID 35152907, 2022). "It was recently demonstrated that hepatic PCK2 mRNA expression increased following the induction of chronic hypoglycemia in fetal sheep and that this was associated with a decrease in circulating insulin and an increase in plasma cortisol." (PMID 35681299, 2022).